EGFR (epidermal growth factor receptor)
Diseases named in the same sentence as EGFR in open-access papers (continued):
Sharing a sentence is not in itself a finding about the gene and the disease.
lung adenocarcinoma (continued). "In lung adenocarcinoma, nuclear EGFR expression has been associated with poor clinical outcome and chemo-resistance." (PMID 28415726, 2017). "Of the 89 lung adenocarcinoma patients, 72 underwent testing for epidermal growth factor receptor (EGFR) mutation and anaplastic lymphoma kinase (ALK) rearrangement." (PMID 29156821, 2017). "In this study, we detected a correlation between YAP1 level and EGFR mutation status in lung adenocarcinoma tissues." (PMID 29163769, 2017). "ADx-SuperARMS EGFR assay is likely to be a highly sensitive and specific method to noninvasively detect plasma EGFR mutations of patients with advanced lung adenocarcinoma." (PMID 28829813, 2017). "Epidermal growth factor receptor (EGFR) mutations are common in lung adenocarcinoma (ADC) but rare in squamous cell carcinoma (SQC)." (PMID 28591695, 2017). "EGFR mutation is one of the most common driver mutations in lung adenocarcinoma, and EGFR-mutated adenocarcinoma is characterized by East-Asian ethnicity, female gender, and non/light-smoking history." (PMID 28894699, 2017). "We performed RHOB immunohistochemistry analysis on 96 lung tumor biopsies collected before any treatment from a series of EGFR‐mutated lung adenocarcinoma." (PMID 28003335, 2017). "EGFR-activating mutations are found with high frequency of 40 to 55 % lung adenocarcinomas in East Asia in which tumor cells are dependent on EGFR signaling." (PMID 29163769, 2017). "Afatinib is effective as a first-line therapy for advanced EGFR mutation-positive lung adenocarcinoma." (PMID 29163842, 2017). "Significant positive correlations between Pellino-1 and Slug or Snail expression were consistently observed in lung adenocarcinoma when separately analyzed according to the EGFR mutation status." (PMID 28009353, 2017). "Considering the potential interference of perioperative therapy, the current study focuses on the pure prognostic impact of EGFR mutations in patients with resected stage I lung adenocarcinoma." (PMID 29065153, 2017). "In the Phase III First-SIGNAL study, high EGFR mutation positivity in plasma was associated with significantly shorter survival in gefitinib-treated patients with lung adenocarcinoma vs low EGFR mutation positivity (P=0.03)." (PMID 28006816, 2017). "Afatinib and erlotinib had a significantly longer progression-free survival than gefitinib in the first-line treatment of patients with lung adenocarcinoma harboring common EGFR-activating mutations." (PMID 27935868, 2017). "A total of 1,801 patients with lung adenocarcinoma diagnosed from January 2011 to December 2014 were screened for EGFR mutation status." (PMID 28380449, 2017). "For example, lung adenocarcinoma with lepidic component is nearly always well- to moderately differentiated and correlates with higher incidence of EGFR mutation." (PMID 29232915, 2017). "In total, 140 patients with advanced EGFR mutation-positive lung adenocarcinoma who had received afatinib as a first-line treatment were enrolled in this study." (PMID 29163842, 2017). "In contrast, activating EGFR-mutation was related to downregulation of DUSP4 in lung adenocarcinomas, and in vitro knockdown of DUSP4 increased cell proliferation." (PMID 29100381, 2017). "In this retrospective study, we performed a radiological analysis to identify some helpful features of EGFR subtype mutation in lung adenocarcinomas in a Chinese cohort of patients." (PMID 28336963, 2017). "In patients with lung adenocarcinoma, the epidermal growth factor receptor (EGFR) mutation status is an important prognostic factor." (PMID 29212235, 2017). "Early resectable lung adenocarcinoma patients with EGFR mutation showed a higher rate of local invasion compared with those harboring wild-type EGFR." (PMID 28253871, 2017). "In general, the frequency of the EML4-ALK fusion gene in lung adenocarcinoma is relatively low compared with that of EGFR mutations in the Japanese population (6.7% and 45%, respectively)." (PMID 29212235, 2017).
lung adenocarcinoma (continued). "For the patients of Asian descent with grade I and II lung adenocarcinoma, the incidence of EGFR mutations was 60.9%, compared to 26.9% for the patients of Asian descent with grade II–III and III histology, a more than two-fold difference (p = 0.006)." (PMID 29232915, 2017). "This article is to evaluate the association of CT features between the wild type and the subtype (exon 19 and 21) of EGFR mutations in patients with lung adenocarcinoma." (PMID 28336963, 2017). "The clinical characteristics of patients with ALK-positive lung adenocarcinoma were similar to those of EGFR-mutated patients." (PMID 29156778, 2017). "In conclusion, using a molecular morphometric approach we were able to demonstrate sub-clonality for KRAS and EGFR mutations in lung adenocarcinoma." (PMID 28501852, 2017). "In lung adenocarcinoma, multiple genetic alterations have already been identified as therapeutic targets, including mutations of the EGFR gene and rearrangement of the ALK and ROS1 genes." (PMID 29290998, 2017). "A strong association has been reported between the expression of the ERβ and EGFR mutations in lung adenocarcinoma." (PMID 28783064, 2017). "Using as a starting point the H1975 lung adenocarcinoma cell line that harbours double mutated (L858R/T790M double mutant) EGFR, we have developed a cellular model to minimise the contribution of confounding influences." (PMID 28141869, 2017). "Activating mutations of epidermal growth factor receptor (EGFR) are identified in about 20% of lung adenocarcinomas in Western countries and 40%–60% of lung adenocarcinomas in East Asia." (PMID 28380449, 2017). "We enrolled stage IV lung adenocarcinoma patients with an EGFR mutation and who had developed acquired resistance to gefitinib and cytotoxic chemotherapy from two university-affiliated hospitals in Taiwan from June 2011 to December 2014." (PMID 28486985, 2017). "In lung adenocarcinoma patients who have activating mutations in the EGFR, it has been reported that EGFR-TKI is an effective therapy." (PMID 28642617, 2017). "In Taiwan, the detection of EGFR mutations in advanced lung adenocarcinoma patients has become a routine procedure." (PMID 29228697, 2017). "EGFR mutations are approximately present in 10% of lung adenocarcinoma in Caucasian population and TKIs based therapy is strongly recommended as first-line treatment in presence of these gene markers." (PMID 28520821, 2017). "We examined 2,219 unselected patients treated in hospitals in Paris and suburbs (France) for metastatic or recurrent lung adenocarcinoma, who were systematically tested for EGFR and other targetable driver mutations in the daily clinical setting." (PMID 28881604, 2017). "Our previous epidemiological study has shown that Japanese males with smoking history has about 7.9 times risk to develop lung adenocarcinoma in EGFR-wt males (unpublished data)." (PMID 29383112, 2017). "The efficacy of tyrosine kinase inhibitors erlotinib and gefitinib in the treatment of EGFR-mutated lung adenocarcinomas was a further boost for the concept of targeted therapy and forced pathology departments to implement EGFR mutation testing." (PMID 28367253, 2017). "The most common somatic aberrations in lung adenocarcinoma are recurrent mutations in the RTK [including epidermal growth factor receptor (EGFR)]/RAS/RAF pathways, which occurred in 76% of cases." (PMID 28306189, 2017). "It was found that in patients with lung adenocarcinoma, the probability of EGFR mutations increases linearly from age 3.7% (18–30 years) to 18.5% (81–100 years), and in female non-smokers, the probability of mutations is higher than in men." (PMID 29137182, 2017). "The frequency of EGFR mutations in lung cancer in Caucasian is 17%1; in American lung adenocarcinoma populations, the frequency is 23%2; and in Chinese lung adenocarcinoma patients, it is 51%3." (PMID 28079142, 2017).
lung adenocarcinoma (continued). "In this study, TTF-1 expression was also associated with EGFR expression in lung adenocarcinoma cell lines." (PMID 29079814, 2017). "In the present study, we have investigated the involvement of IGF1R in acquired high-dose erlotinib resistance in the EGFR-mutated lung adenocarcinoma cell line HCC827." (PMID 28418902, 2017). "Among the patients with lung adenocarcinoma, 14,654 (59.7%) exhibited advanced stage diseases, and 79.7% of these patients had available EGFR mutation data." (PMID 29228697, 2017). "This study aimed to assess the effects of EGFR mutation on local invasion in resectable lung adenocarcinoma." (PMID 28253871, 2017). "These trials established EGFR TKIs as first line systemic therapy for patients with Stage IV lung adenocarcinoma harbouring EGFR sensitizing mutations." (PMID 29312641, 2017). "In conclusion, our data analyzed risk factors of TNM stage III lung adenocarcinoma with EGFR mutations in exon 19 or 21 after radical surgery." (PMID 28380449, 2017). "A total of 1,801 lung adenocarcinomas were analyzed for mutations in EGFR; 35% exhibited mutation of classic EGFR exons." (PMID 28380449, 2017). "The results showed that MAP4K4 was drastically elevated in lung adenocarcinoma independently of KRAS or EGFR mutation status." (PMID 28306189, 2017). "To identify if YAP1 is a possible target for EGFR-dependent lung adenocarcinomas, we investigated the correlation between EGFR mutation status and YAP1 expression in 164 cases of NSCLC tissue." (PMID 29163769, 2017). "This study aimed to identify microRNA (miRNA) signature in relation to mutation status in EGFR gene in early stage of lung adenocarcinoma male patients with smoking history." (PMID 29383112, 2017). "By the end of the follow-up period for the 361 patients diagnosed with BMs from lung adenocarcinoma, 160 (44.3%) had confirmed EGFR mutations and 10 (2.8%) had ALK mutations; one patient had both." (PMID 29050314, 2017). "Recently, we reported that podoplanin-positive CAFs induce primary resistance to EGFR-TKIs in lung adenocarcinomas exhibiting EGFR mutations, with podoplanin playing a functional role in this effect." (PMID 28429795, 2017). "Based on histological type, 40.7% (177/435) of lung adenocarcinoma patients and 10.3% (6/58) of lung squamous cell carcinoma patients had EGFR mutations." (PMID 28079142, 2017). "This is a known hotspot mutation and accounts for more than 40% of EGFR mutations reported in Asian lung adenocarcinoma patients." (PMID 27767028, 2016). "This retrospective cohort study included 77 lung adenocarcinoma patients with common EGFR mutations from December 2012 to February 2015." (PMID 27368002, 2016). "EGFR mutations in lung adenocarcinoma are more frequent in East Asians compared to other populations." (PMID 27501781, 2016). "Of 1127 patients with advanced lung adenocarcinoma harboring EGFR 19 del or L858R mutations, 532 received EGFR-TKI treatment and were included in this study." (PMID 27001083, 2016). "Other studies have reported that whole-body TLG was an independent prognostic factor in advanced lung adenocarcinoma patients with the EGFR mutation." (PMID 27336755, 2016). "The frequency of these driver mutations were identical to the previous report that analyzed unselected Japanese lung adenocarcinoma patients; EGFR mutation, KRAS mutation, ALK fusion, or HER2 mutation were identified in 67.7% (216/319)." (PMID 27100677, 2016). "Twist expressed in lung adenocarcinoma cell lines with EGFR mutation showed increased cell mobility." (PMID 27018053, 2016). "Secondary EGFR c.2369C > T (p.T790M) mutation is detected in 50–60% of lung adenocarcinoma patients after acquiring resistance to EGFR TKIs." (PMID 27734950, 2016). "In summary, our findings demonstrated that lung adenocarcinoma with clear cell component is a rare, malignant tumor with poor prognosis and displays more frequent EGFR and KRAS mutations." (PMID 27013585, 2016).
lung adenocarcinoma (continued). "On the other hand, recent studies showed that EGFR mutations were more frequent in stage IV disease among advanced or recurrent lung adenocarcinomas." (PMID 27861565, 2016). "Among 134 patients with EGFR-mutated advanced lung adenocarcinoma, 34 (25.4%) patients developed BM during the course of EGFR-TKIs treatment and 100 (74.6%) patients didn't." (PMID 27626317, 2016). "The HER-2 mutation rate was 4.8 % among EGFR wild-type lung adenocarcinoma patients in China, and 6.7 % among driver genes, triple-negative lung adenocarcinoma." (PMID 27793199, 2016). "Among the three groups, we evaluated only patients with stage IIIB–IV lung adenocarcinoma who had EGFR mutations (n = 126), KRAS mutations (n = 35), or ALK rearrangements (n = 47)." (PMID 27518729, 2016). "All patients had been diagnosed with adenocarcinoma of the lung with activating EGFR mutations at initial diagnosis." (PMID 27821131, 2016). "Two common EGFR somatic alterations, the L858R mutation in exon 21 and exon 19 in-frame deletions encompassing amino acids 747 to 749, represent about 90% of EGFR mutations in lung adenocarcinoma, and predict clinical responses to EGFR-TKIs." (PMID 26883194, 2016). "We retrospectively analyzed 1004 consecutive patients who were diagnosed with lung adenocarcinomas and tested for EGFR mutations between June 2011 and December 2014." (PMID 27861565, 2016). "Lung adenocarcinoma patients harboring kinase domain mutations in Epidermal growth factor receptor (EGFR) have significant clinical benefit from EGFR-targeted tyrosine kinase inhibitors (TKIs)." (PMID 27494838, 2016). "Lung adenocarcinoma driven by somatic EGFR mutations is more prevalent in East Asians (30–50%) than in European/Americans (10–20%)." (PMID 27501781, 2016). "In summary, our results showed that the content of mutant EGFR DNA is associated with the clinical response to EGFR-TKIs in lung adenocarcinoma patients with common EGFR mutations, especially in patients with exon 19 deletion mutations." (PMID 27368002, 2016). "Many such treatments were discovered before the mechanism for their effectiveness was recognized, such as gefitinib and mutated epidermal growth factor receptor (EGFR) in lung adenocarcinoma." (PMID 27784327, 2016). "Positive and partially positive TTF-1 expression in lung adenocarcinoma patients correlates with EGFR mutations (exon 19 and 21)." (PMID 26806377, 2016). "CT scan showed new lesions in the left upper lung lobe and the right main bronchus, and wedge resection of the left upper lobe revealed a lung adenocarcinoma harbouring an EGFR exon 19 deletion and exon 20 T790M mutation." (PMID 27533086, 2016). "Serial plasma samples from lung adenocarcinoma patients treated with TKIs were used to quantify EGFR and KRAS mutations in circulating DNA by digital PCR." (PMID 27640882, 2016). "ARMS analysis was used to detect HER-2 exon 20 mutations in 456 cases of wild-type EGFR lung adenocarcinoma; 22 (4.8 %) were found to be positive." (PMID 27793199, 2016). "EGFR mutations in six lung adenocarcinomas were 100% concordant according to data from TIC‐seq and the PCR‐Invader assay." (PMID 27774772, 2016). "Elucidation of novel mechanisms underlying the acquired resistance to EGFR-TKIs is important for developing personalized therapeutics to treat patients with lung adenocarcinoma." (PMID 27494877, 2016). "Some reports revealed that the EGFR mutation is a prognostic factor in lung adenocarcinoma patients who are treated with chemotherapy." (PMID 26923333, 2016). "The purpose of this study was to define histological features determining the malignant potential of EGFR-mutated lung adenocarcinoma (LADC)." (PMID 27861549, 2016). "In this study, we evaluated the association of EGFR mutations with stage at diagnosis in lung adenocarcinomas." (PMID 27861565, 2016).
lung adenocarcinoma (continued). "Constitutive activation of the EGFR tyrosine kinase as a result of genetic mutations within it was first reported in a subgroup of lung adenocarcinoma patients." (PMID 26747090, 2016). "EGFR mutation status was assessed for lung adenocarcinoma samples (formalin fixed- paraffin embedded samples) using qPCR, SNaPshot and NGS (Ion TorrentTM) techniques." (PMID 27215400, 2016). "Previous studies reported that serum CEA levels were associated with EGFR mutations in patients with lung adenocarcinomas." (PMID 27563816, 2016). "In the present study, we did show that EGFR mutations were significantly associated with early stage disease at diagnosis after adjusting for screening in a cohort of 1004 patients with lung adenocarcinomas." (PMID 27861565, 2016). "Some Food and Drug Administration (FDA) approved drugs for stage IV lung adenocarcinoma target molecular alterations including mutations in epidermal growth factor receptor (EGFR) and rearrangements of anaplastic lymphoma kinase (ALK)." (PMID 27220886, 2016). "In lung adenocarcinoma, multiple genetic alterations have already been identified as therapeutic targets, including mutations of the EGFR gene and rearrangements of the ALK and ROS1 genes." (PMID 26936516, 2016). "We also investigated the association between EGFR status and survival in the 116 patients with stage I lung adenocarcinoma; for whom 110 (95 %) had EGFR mutation analyses available, which showed 61 (53 %) to have EGFR mutations." (PMID 27842505, 2016). "The presence of EGFR mutations is significantly associated with early stage disease at initial diagnosis in lung adenocarcinomas after adjusting for age, sex, smoking status, and screening." (PMID 27861565, 2016). "EGFR mutations are found in 30% to 50% of lung adenocarcinomas, with the most common mutations being deletion in exon 19 (Ex19 in 45% patients) and a mutation in exon 21 L858R point (Ex21 in 40% patients)." (PMID 27527915, 2016). "In conclusion, TLGWBR is a promising parameter for prognostic stratification of patients with advanced lung adenocarcinoma and EGFR status; however, it cannot be used to further stratify the risk of worse OS for patients with the EGFR mutation." (PMID 27336755, 2016). "GA and GA + AA genotypes of IGF1R rs2229765 had significant association with EGFR mutation in female lung adenocarcinoma patients (OR = 0.35, 95% CI = 0.15–0.82 and OR = 0.39, 95% CI = 0.17–0.87, respectively)." (PMID 27213344, 2016). "EGFR mutations were reported with a frequency of around 10 % for total lung adenocarcinoma but up to 40 % in some Asian cohorts – mainly represented by exon 19 deletions and one exon 21 point substitution c.2369C > T (L858R)." (PMID 27215400, 2016). "Survival analysis regarding TLGWBR, and other factors in advanced lung adenocarcinoma patients stratified using EGFR mutation status, were evaluated." (PMID 27336755, 2016). "Here we investigate genetic factors underlying the risk of this disease by conducting a genome-wide association study, followed by two validation studies, in 3,173 Japanese patients with EGFR mutation-positive lung adenocarcinoma and 15,158 controls." (PMID 27501781, 2016). "Here, our results indicated that ddPCR is a highly sensitive method for EGFR mutation analysis with ctDNA for advanced lung adenocarcinoma patients, with a detection limit 0.04%." (PMID 26989078, 2016). "This study indicates that multiple genetic factors underlie the risk of lung adenocarcinomas with EGFR mutations." (PMID 27501781, 2016). "In a more recent study in Norway, the prevalence of EGFR mutations in lung adenocarcinomas was found to be 9.4 %." (PMID 27655296, 2016). "The most representative examples are gefitinib/erlotinib and crizotinib for lung adenocarcinomas harboring EGFR mutations and ALK/ROS1 fusion, respectively." (PMID 27223439, 2016). "Despite these findings, a clear relationship between EGFR mutation and the BM of lung adenocarcinomas remains to be determined." (PMID 27486770, 2016).